BANCR (BRAF-activated non-protein coding RNA)
Diseases named in the same sentence as BANCR in open-access papers (continued):
Sharing a sentence is not in itself a finding about the gene and the disease.
cancer (continued). "In addition, BANCR is also dysregulated in a variety of cancers, including liver, lung, and colorectal cancer, and is associated with poor patient prognosis." (PMID 39408810, 2024). "It has been previously revealed that LINC00586 (BANCR) was aberrantly in various cancers." (PMID 35586041, 2022). "On the other hand, BANCR has been shown to be involved in the therapeutic effects of some anti-cancer substances such as Fentanyl and deoxyelephantopin signifying the importance of identification of the possible involved mechanisms to apply these substances in the clinical settings." (PMID 34409032, 2021). "Consequences of BANCR up-/down-regulation in animal models of cancer." (PMID 34409032, 2021). "In brief, BANCR is an lncRNA with bidirectional effects in the pathogenesis of cancers." (PMID 34409032, 2021). "Increasing numbers of studies about BANCR in various cancers have determined its importance in the tumorigenesis through affecting cell proliferation, migration, invasion, apoptosis, and epithelial to mesenchymal transition (EMT), which are crucial for disease prognosis." (PMID 34409032, 2021). "After several years of investigation, an increasing number of studies have reported that BANCR could serve as both an oncogene and tumor suppressor gene in various cancers." (PMID 32907530, 2020). "Finally, the detailed molecular biological mechanisms of BANCR in various cancers were discussed and summarized." (PMID 32907530, 2020). "Thus, a meta-analysis was performed to investigate the prognostic value of BANCR in various cancers." (PMID 32907530, 2020). "Previous studies revealed the dysregulation of BANCR in various cancers." (PMID 30144787, 2018). "Importantly, BANCR is responsible for proliferation, migration, invasion and apoptosis of cancer cells." (PMID 29212285, 2017). "Furthermore, BANCR promotes the proliferation and migration of cancer cells and inhibits cell apoptosis." (PMID 29212285, 2017). "Evidence suggests that BANCR might play important roles in cancer growth and metastasis and may be a prognostic indicator in certain cancers." (PMID 28009984, 2017). "In contrast, overexpression of NF-κB1 could reverse the effect of BANCR on cancer cell growth and apoptosis." (PMID 29212285, 2017). "Since then, increasing studies about BANCR in cancer progression were reported." (PMID 29212285, 2017). "Additional studies are needed to confirm the function of BANCR in various cancers." (PMID 28009984, 2017). "These evidences suggest that BANCR may be involved in different signaling pathways and plays its unique role in each cancer." (PMID 27514530, 2016). "Although samples from only six patients were used in the present study and the results may not be entirely accurate due to type I or II errors, the present data suggest a possible oncogenic role of BANCR in several human cancers." (PMID 25289082, 2014). "However, the specific role of BANCR in modulating metabolic reprogramming of cancer cells remains unclear." (PMID 39894218, 2025). "In addition, STM2457 may play an anticancer role in BANCR and other types of cancers with high levels of m6A, and its efficacy and safety should be evaluated in more clinically relevant cancer models in the future." (PMID 37998732, 2023). "Besides, BANCR silencing has increased anti-cancer effects of this agent in animal models." (PMID 34409032, 2021). "Furthermore, the functions and mechanisms of BANCR in cancer cells have been clarified." (PMID 29212285, 2017). "BANCR may act as the biomarker and therapeutic target for human cancers." (PMID 29212285, 2017). "The expression of BANCR was significantly decreased in NSCLC tissues, suggesting that its downregulation may be a negative prognostic factor for NSCLC patients, and indicative of poor survival rates and a higher risk for cancer metastasis." (PMID 24655544, 2014).
cancer (continued). "Patients with higher BANCR expression had a higher rate of extracapsular invasion and lateral LNM in carcinoma tissue and a lower frequency of bilateral tumors and multifocality in normal adjacent tissue." (PMID 32593310, 2020). "Emerging evidence demonstrates that lncRNAs, including BANCR, may regulate EMT processes in several cancer types." (PMID 26758762, 2016). "Altered BANCR expression in the HCT116 and Caco-2 cells was found to affect migration and thus, the current results are consistent with those of a previous study, indicating that BANCR expression enhances the aggressive biological behaviour of cancer cells of various origins." (PMID 25013510, 2014).
infection (2 papers, 2014 to 2019). The state of being infected such as from the introduction of a foreign agent such as serum, vaccine, antigenic substance or organism. "We also observed strong upregulation of BANCR in Müller cells at 24 h after infection with the virulent strains of T. gondii that we studied." (PMID 31547203, 2019). "Other lncRNAs (i.e., BANCR, GAS5, GSTT1-AS1, PVT1, RMRP, and SNHG15) increased at one or more time-points during infection; BANCR was highly increased in infected cells, but only at 24 h." (PMID 31547203, 2019). "The results revealed that following infection with LV-BANCR, the BANCR expression level was significantly upregulated compared with the LV-NC (P<0.05)." (PMID 25289082, 2014). "Following infection with LV-BANCR-323 and LV-BANCR-540, the BANCR expression level was significantly downregulated compared with the LV-NC (P<0.05)." (PMID 25289082, 2014).
BANCR also shares sentences with these, for which no sentence is quoted: esophageal squamous cell carcinoma (3 papers); esophageal cancer (2); autoimmune disease (1); bronchial carcinoma (1); cardiovascular diseases (1); Cirrhosis (1); cutaneous melanoma (1); digestive system cancer (1); gastric tumor (1); Hyperglycemia (1); liver neoplasm (1); metabolic disorders (1); thyroid (1); thyroid tumor (1).